FOXP3 (forkhead box P3)
Diseases named in the same sentence as FOXP3 in open-access papers (continued):
Sharing a sentence is not in itself a finding about the gene and the disease.
tumor (continued). "We chose antibody clones that showed appropriate regional (e.g., splenic white pulp) and subcellular localization (e.g., cell membrane for CD3ε, CD4 and CD8α and nucleus for FoxP3) in spleen and tumor tissue." (PMID 38605049, 2024). "The custom mouse panel was designed to detect T cell biomarkers CD3ε, CD4, CD8α and FoxP3 and was evaluated on murine tumor specimens with varying levels of T cell infiltration." (PMID 38605049, 2024). "This relationship promotes tumor immune evasion by inducing FoxP3 phenotype regulation, consequently suppressing the immune microenvironment." (PMID 39290709, 2024). "In parallel, mIF showed an aggregation of CD4+/FOXP3+ Treg cells in tumor tissues of subtype A, but almost invisible in the tumor tissue of the other three subtypes." (PMID 39060379, 2024). "Conversely, the high Foxp3/CD3 or Foxp3/CD8 ratio in tumor tissues has been reported as a poor prognostic factor, suggesting that the balance between CD8+ T cells and Tregs is important in tumor immunity." (PMID 38783281, 2024). "This can be partly attributed to the fact that in some tumor models FoxP3 is expressed in other lymphoid and myeloid cells, and in some non-hematopoietic cells such as cancer cells." (PMID 38605049, 2024). "Programmed cell death protein 1 (PD-1) is overexpressed on activated tumor-infiltrating T lymphocytes, including regulatory T cells that suppress immune responses via FOXP3 expression." (PMID 39772246, 2024). "These investigations propose that FOXP3 functions as a co-activator to facilitate the Wnt-β-catenin signaling pathway and induce epithelial-mesenchymal transition, thereby promoting tumor growth and metastasis in NSCLC." (PMID 39372398, 2024). "It has been shown that Foxp3 works synergistically to control the recruitment of chemokine CCL5 to Treg cells in the tumor microenvironment to promote the immune escape of PDAC." (PMID 38919615, 2024). "In one of the patients from each of the lead-in groups (A-2 and S-2), increases in CD19+ tumor-infiltrating B cells, CD68+ tumor-associated macrophages, CD4+ and CD8+ T cells (CD3+), as well as FOXP3+ regulatory T cells, were also observed." (PMID 38672538, 2024). "As expected, we observed complete depletion of total CD4+ T cells and Tregs (defined as Foxp3+ CD25+ CD4+ T cells) in the tumor and TdLN in both the Tx + ɑCD4 and the ɑCD4 groups." (PMID 38429261, 2024). "Immunohistochemical analysis and multiplex immunofluorescence for CD4, CD8, CD25, FOXP3, and PD‐L1 in the tumor were used to identify multiple tumor‐infiltrating immune cells (TIIC), Tregs, and TC." (PMID 39264227, 2024). "In comparison to ARID1A -proficient patients, patients with ARID1A deficiency exhibited a significant increase in the infiltration levels of CD8 + cells, CD163 + cells and FOXP3 + cells within the tumor tissue." (PMID 38555560, 2024). "We analyzed the mRNA expression level of FOXP3 in lung tissues of the mice of the two groups, and found that FOXP3 as well as PD-L2 expression levels were elevated in tumor tissues of LLC-PD-L2-bearing mice than that in LLC-NC-bearing mice." (PMID 39042313, 2024). "To confirm that RANKL/RANK signaling recruits Tregs via the CCL20–CCR6 pathway, we discovered that CCR6 and FOXP3 were colocalized in the blood and tumor tissue of CRC." (PMID 38902257, 2024). "RE1-Silencing Transcription Factor corepressor (CoREST) complexes, containing HDAC1 or HDAC2, impede the functionality of FOXP3+Tregs through deacetylation and augment the body’s anti-tumor capacity." (PMID 39144146, 2024). "A low dNLR is associated with significantly increased tumor-associated CD8+, FOXP3+, and PD-1+ immune cells and favorable outcomes." (PMID 39123434, 2024). "First, Foxp3 exhibits distinct binding patterns during Treg cell activation or adaptation to the tumor environment in vivo." (PMID 39882241, 2024).
tumor (continued). "Immunohistochemistry highlights an abundance of VISTA-expressing myeloid cells clustering at the tumor–cerebellar border, while T-cells are scarce and express FOXP3." (PMID 39123357, 2024). "In CRC, Foxp3+CD25+CD4+ Tregs inhibit anti-tumor immune responses in CRC patients and mediate immune evasion in CRC." (PMID 39262952, 2024). "Cytotoxic effector CD8+ T cells are essential for direct elimination of tumor cells, while Foxp3+ Treg cells act as negative regulators of the immune response, suppressing effector T cell activity and promoting tumor tolerance." (PMID 38892375, 2024). "Analysis of specific surface markers of Tregs [GITR, HLA-DR, CD45RO, CD152, and CD45RA and FOXP3] also showed that there is a steady increase in the number of Tregs in both peripheral blood and tumor microenvironment." (PMID 38571964, 2024). "Ruminococcaceae improves the infiltration of CD8+ T cells within tumors, induces the differentiation of effector CD4+ and CD8+ T cells, and enhances the ratio of CD8+/FOXP3+CD4+ in tumor-infiltrating T cells." (PMID 38617841, 2024). "The immunophenotyping of tumor-infiltrated immune cells showed higher levels of Foxp3+ Treg in the α-PD-1 antibody-treated group consuming high Zn as compared to the treatment-only group." (PMID 39247196, 2024). "Based on this information, it can be assumed that the immunosuppressive function of Foxp3+CD4+ T cells in tumour tissue can be driven by PD-L1 expression in these cells localised in tumour islets." (PMID 39409156, 2024). "The densities of regulatory T cells (Treg; CD3+CD4+FoxP3+ cell) were significantly decreased and almost disappeared in the tumor microenvironment of posttreatment tissue compared with pretreatment tissue." (PMID 38228697, 2024). "Within the CD4+ T cell compartment, there were more T effector/memory (TEM; CD44+, CD62L-) and less T regulatory (Treg; FoxP3+) cells in CR705Parp7KO compared with CR705Cas9 tumours." (PMID 39867896, 2024). "Regulatory T cells (Tregs) expressing the transcription factor FoxP3 are essential for maintaining immunological balance and are a significant component of the immunosuppressive tumor microenvironment (TME)." (PMID 38509593, 2024). "Altogether, these data showed that BCCs and SCCs share a dense T cell infiltrate of similar composition regarding broad T cell subsets, namely, CD8+, CD4+, and FoxP3+, essentially confined to the tumor periphery." (PMID 38891095, 2024). "The FOXP3+ TIL density was increased in PD-L1-strong-positive tumor specimens before and after EGFR-TKI treatment compared with the corresponding PD-L1-negative or -low-positive tumor specimens." (PMID 38674427, 2024). "Foxp3-expressing regulatory T (Treg) cells represent the most highly immunosuppressive cell in the tumor microenvironment (TME) that halts effective anti-tumor immunity." (PMID 39272810, 2024). "Utilization of inhibition by Ep300 is sufficient to reduce Foxp3 and decrease the function and homeostasis of Tregs, thereby increasing anti-tumor immunity." (PMID 39227959, 2024). "In our current study, we showed that targeting of intratumoral Tregs with ASO FOXP3 was accompanied by significant reduction in expression of exhaustion molecules on the tumor T cells, in vivo in tumor models and in vitro in human primary tumor samples." (PMID 39234236, 2024). "The percentages of Foxp3+ Treg cells, CD23+ GC B cells, DC-LAMP+ mature DCs, CD20+ B cells, CD8+ T cells, PD-1+ cells and CD20+ FOXP3+ cells were significantly greater in TLSs than in the tumour stroma." (PMID 39136032, 2024). "To delineate the immune context of LLT1TC high patients, we evaluated the distribution of CD4+ T cells, CD8+ T cells, Foxp3+ Tregs, CD68+ tumor‐associated macrophages, and CD19+ B cells." (PMID 38502058, 2024). "They employed automated deep learning to analyze CD3, CD8, and FOXP3 markers across various tumor regions." (PMID 39555450, 2024).
tumor (continued). "The study revealed a higher expression of FoxP3 in the tumor bed, contrasting with the predominant expression of CD8 in the stroma of breast tissue." (PMID 39769501, 2024). "NAPSL.p@OVA vaccination effectively reduced regulatory T cells (Tregs, CD3+CD4+ Foxp3+ T cells) and myeloid-derived suppressor cells (MDSCs, CD11b+Gr-1+) in tumor tissues." (PMID 38764014, 2024). "FoxP3+ stable Tregs, a type of immunosuppressive cells, demonstrate anti-tumor benefits by inhibiting tumor-promoting inflammation." (PMID 38509593, 2024). "This approach was used to assess the cells collected from tumor tissues and measure CD4 and Foxp3 expression using flow cytometry, where the aCD20@ExoCTX/siPDK4 group significantly inhibited the activity of Treg cells in tumor tissues compared to other groups." (PMID 39004737, 2024). "We have observed a positive correlation between those patients with high FOXP3+ infiltration in tumor and those with high expression of LGALS3 in tumor (R = 0.6, P = 0.019)." (PMID 37567864, 2024). "In HBV-infected patients, circulating and tumor-infiltrating FoxP3+Tregs are enriched, exerting a suppressive effect on antitumor immunity." (PMID 39026969, 2024). "Treg exhibits instability when it loses the transcription factor Foxp3, which can promote tumor immunity, and a variety of ubiquitinases/deubiquitinases can regulate Treg by modulating Foxp3." (PMID 39253578, 2024). "The tumor tissue of 182 patients was stained by double immunohistochemistry for FOXP3, CD4, and CD8, and the number of different phenotypes was analyzed microscopically." (PMID 39200145, 2024). "CD4, CD25, and FOXP3 are essential for the development, maturation and functioning of Tregs and provide a suitable microenvironment facilitating tumor escape." (PMID 39264227, 2024). "Certain researchers have employed ablation of Foxp3+ Tregs to arouse tumor-antagonizing immunity, which was frustratingly devoid of clear translational potential and had diverse adverse effects." (PMID 39227959, 2024). "High expression of PD-L1 on tumor endothelial cells reduces CD8+ T cell infiltration and increases the aggregate of forkhead box P3 (FoxP3)+ Tregs in the tumor mass; anlotinib downregulates PD-L1 expression on tumor endothelial cells." (PMID 39325128, 2024). "We conducted IHC staining of CCL11, CD4, and Foxp3 proteins in serial sections of the same tumor tissues from BRCA patients." (PMID 38305920, 2024). "In conclusion, this work revealed the stable expression of FOXP3 in tumor epithelial cells, marking a distinct subset." (PMID 38047300, 2024). "Note that in 4T1 and B16F10 tumor models, the relative abundance of FoxP3+ cells is higher than that of CD4+ and CD3ε+ cells in most runs." (PMID 38605049, 2024). "FOXP3 overexpression in Treg cells can promote tumor cell growth in non-small cell lung cancer (NSCLC)." (PMID 39534095, 2024). "We furtherly double-stained macrophages (CD163+ CD68+), helper T cell (CD3+ CD4+), cytotoxic T cell (CD3+ CD8+), and Treg cell (CD4+ FOXP3+) of subcutaneous tumor tissues and examined the cells using immunofluorescence (IF)." (PMID 38483163, 2024). "Patients with lower TLS in the tumor core or lower FoxP3+ T cells had better overall survival in the trastuzumab-exposed group." (PMID 39313575, 2024). "FOXP3 is an essential element of complex mechanisms that modulate the immune response and consequently impose tumor behavior." (PMID 38674427, 2024). "As the crucial component of tumour microenvironment, FOXP3+ Treg cell infiltration into a tumour can suppress anti‐tumour immunity, thereby inducing immune evasion and promoting tumour progression." (PMID 38041531, 2024). "On the other hand, FOXP3 has been considered to reduce or prevent inflammation-mediated tumor progression." (PMID 38308298, 2024). "This study primarily explored the immunoexpression of TGFβ, FoxP3, VEGF, and CD31 in malignant CMT and their associations with tumor clinicopathological features." (PMID 39165025, 2024).
tumor (continued). "In our previous study, we found that PD-L1 expression evaluated by TPS, IC, and CPS was significantly associated with the CD4+ T cells, Foxp3+CD4+ T cells, CD8+ T cells and M2 macrophage infiltration in the whole tumour tissue." (PMID 39409156, 2024). "Foxp3+ regulatory T cells (Treg) promote tumor immune escape by forming a suppressive tumor microenvironment." (PMID 39068665, 2024). "FOXP3-expressing regulatory T (Treg) cells, which suppress aberrant immune response against self-antigens, also suppress anti-tumor immune response." (PMID 39664195, 2024). "As expected, Treg (CD4T_FOXP3) cells were significantly more abundant in tumor tissue compared to adjacent normal tissue." (PMID 38552055, 2024). "Here, we show in a mouse tumor model representative of human lymphocyte–depleted cancer that RT enhanced spontaneous priming of thymus-derived (FOXP3+Helios+) Tregs by the tumor." (PMID 38349740, 2024). "CAFs also induced immunosuppressive tumor infiltrating lymphocytes (TILs), including CD8+ T cells and FoxP3+ T cells (regulatory T cells, Tregs) in both allograft tumor models and clinical esophageal cancer specimens." (PMID 38555315, 2024). "PDPN-positive CAFs are also associated with an immunosuppressive tumor microenvironment, characterized by high levels of CD204+ tumor-associated macrophages and a low CD8/FOXP3 T-cell ratio." (PMID 40741180, 2024). "CD8B/FOXP3 expression ratio and intra-tumor CD8+ T cell density were positively correlated, indicating consistency between transcriptomic and proteomic data." (PMID 39013886, 2024). "To evaluate the opposing tumor immune effects of GzmB+ Treg vs GzmB+ Th cells, we determined the ratio of GzmB+FoxP3+/GzmB+FoxP- CD4 T cells." (PMID 38968186, 2024). "On the other hand, the tumor infiltrating immune suppressive cells such as FoxP3+ Tregs and CD68+ macrophages were correlated with inferior outcome." (PMID 38017652, 2024). "Together with the present findings, among CD4+ helper T cell components, activated effector CD25+FOXP3+CD45RA− T cells possibly play crucial roles in tumor chemosensitivity." (PMID 39232704, 2024). "Although female patients had significantly lower tumor mutational and neoantigen burden than males, pretreatment tumor tissues of female patients had markedly higher CD4, CD4/FOXP3, and CD4/FOXP3/PD‐L1 expression level than male patients." (PMID 38899854, 2024). "In HCC, lower methylation of FOXP3 promoter via DNA methyl transferase (DNMT1) is positively linked to a higher percentage of intra-tumoral Treg levels and tumor growth." (PMID 38571964, 2024). "Th17 cells cloned from T lymphocytes in human tumor tissues can differentiate into FoxP3+ Tregs and repeatedly stimulate T-cell receptors in vitro." (PMID 39534095, 2024). "As of now, research has shown that Foxp3+ Treg expression, altered glucose metabolism, or a hypoxic tumor microenvironment all affect Foxp3+ Treg function in the bodies of tumor patients." (PMID 38919615, 2024). "Apart from FoxP3+ Tregs, myeloid-derived suppressor cells (MDSCs) and tumor-infiltrating Tregs contribute to the cessation of classic and anti-tumor immunities and facilitates the secretion of soluble membrane-bound immunosuppressive molecules." (PMID 37605389, 2024). "Regulatory T cells, identified by the expression of CD4, CD25, and Foxp3 proteins, play a pivotal role in tumor progression by suppressing immune responses specifically targeting tumors." (PMID 38817895, 2024). "Patients with ARID1A deficiency, compared to ARID1A-proficient patients, exhibited increased infiltration levels of CD8 + P value < 0.0001), CD163 + P value < 0.001), and FOXP3 + P value < 0.001).cells within the tumor tissue." (PMID 38555560, 2024). "The proportion of tumor-infiltrating Tregs was higher in tumor-bearing Tmed4ΔTreg mice, whose Tregs derived from dLNs, and the tumors had significantly lower Foxp3 expression levels." (PMID 39480507, 2024).
tumor (continued). "The ratio of tumor-infiltrating CD8+/Foxp3+CD25+ Tregs and the frequency of cytotoxic IFNγ+ CD8+ cells were significantly higher in the iPSC/RT subgroup, suggesting a predominance of immune system activation over suppression within the tumor microenvironment." (PMID 38821980, 2024). "CD4+/CD25+/FOXP3+ Treg cells suppress the immune system and promote tumor progression by reducing the anticancer immunity of CD4+ T or CD8+ effector T cells." (PMID 39534095, 2024). "There was also a positive correlation between tumor size and the number of CD163+ M2 macrophages (p = .005) and a positive association between the number of FoxP3+ Treg cells and the histological grade of the tumors (p = .042)." (PMID 38954689, 2024). "Tumours with positive PD-L1 IC expression were more likely to have high Foxp3+CD4+ T cell infiltration in tumour islets." (PMID 39409156, 2024). "Forkhead box protein 3 (FOXP3), traditionally recognized as a specific transcription factor for regulatory T cells (Tregs), has also been identified in various tumor epithelial cells (named as cancer-FOXP3, c-FOXP3)." (PMID 38047300, 2024). "In contrast, increased CD8+ T cells and delayed tumor progression in the sporadic FibΔZeb1 tumors showed an unaffected FOXP3+ infiltration, pointing towards Tregs as part of a compensatory immunomodulatory mechanism in the AOM/DSS model." (PMID 38937629, 2024). "The CD4+ T cell subclass, i.e., CD4+ CD25+ Foxp3+ Tregs, plays an important role in the tumor regulation of the immune response." (PMID 39329710, 2024). "Tregs characterized by FOXP3+ CD25+ CD4+ expression promote tumor immune evasion by suppressing the immune responses of CD8+ and CD4+ T cells." (PMID 39263534, 2024). "Inhibition of FOXP3+Tregs in TME can prevent CD8 T cells from effectively responding to tumor cells." (PMID 39256364, 2024). "The effects and mechanisms of FOXP3 on U87 cell proliferation in vivo were investigated using subcutaneous tumor formation and in situ tumor formation models." (PMID 38561331, 2024). "All in all, the correlation between IFI27 expression and FOXP3 was supported by clinical samples and TCGA BCa patient data, suggesting that the IFI27/PD-1/FOXP3 axis was involved in the modulation of anti-tumor immune processes in BCa." (PMID 39668835, 2024). "Meanwhile, USP11/USP20-FOXP3 presents potential therapeutic target for inhibiting FOXP3-induced tumor immune evasion, as FOXP3 itself cannot be targeted due to its important role in autoimmunity." (PMID 38806474, 2024). "This is even though we have clarified the specific regulatory mechanisms of some Foxp3 transcription processes in different tumor types." (PMID 38919615, 2024). "The heatmap shows that genes upregulated in tumor-infiltrating Tregs were reduced in cKO mice, while genes downregulated by FOXP3 exhibited increased expression in the cKO group." (PMID 39446493, 2024). "Six tumor-infiltrating CD4+ T-cell clusters (CD4+_FOXP3, CD4+_CCR7, CD4+_LMNA, CD4+_ISG15, CD4+_CXCL13 and CD4+_MKI67) were identified after data filtering, integration, unsupervised clustering and annotation." (PMID 38383773, 2024). "Ablation of IL-33 reprograms Tregs to upregulate IFNγ expression and maintain Foxp3 expression, consistent with a “fragile” phenotype, which exhibits reduced suppressive function in vivo, thereby accelerating tumor regression." (PMID 39227959, 2024). "The IFN-γ-treated mice showed increased FoxP3 positive staining in the grafted tumor tissue with fewer CD8+ T cells than in vehicle-treated mice." (PMID 38540186, 2024). "The FOXP3+ T-cell density was comparable in biopsies compared to the tumor surface, but significantly different in the tumor surface compared to the tumor center (p < 0.001)." (PMID 39444424, 2024). "We found that this tumor type spontaneously induced priming and tumor infiltration by effector phenotype, thymus-derived (FOXP3+Helios+) Tregs, which was exacerbated by RT and prevented CTL-mediated tumor control." (PMID 38349740, 2024).